RAD51D (RAD51 paralog D)
Diseases named in the same sentence as RAD51D in open-access papers (continued):
Sharing a sentence is not in itself a finding about the gene and the disease.
breast cancer (continued). "Among them, CDKN2A showed a contribution to breast cancer risk that was comparable to that conferred by BRCA2, whereas RAD51C, RAD51D, BRIP1 were proven to be responsible for an increase in ovarian cancer risk." (PMID 31936873, 2020). "For example, PVs in ATM and BRCA1 were significantly associated with >twofold increased risk for colorectal cancer and PVs in RAD51D and CDKN2A were significantly associated with >twofold increased risk for breast cancer." (PMID 31406321, 2020). "This occurrence likely facilitated the African American breast cancer associations regarding ATM c.2289T>C (p.F763L), BRCA2 c.2926_2927delinsAT (p.S976I) and RAD51D c.251T>A (p.L84H)." (PMID 32866190, 2020). "The purpose of this study was to estimate precise age-specific tubo-ovarian carcinoma (TOC) and breast cancer (BC) risks for carriers of pathogenic variants in RAD51C and RAD51D." (PMID 32107557, 2020). "This approach is particularly valuable when counseling individuals with variants in moderate-penetrance breast cancer genes like CHEK2, ATM, RAD51C, RAD51D, and BARD1, since the relative effect of risk factors is expected to be higher than in individuals with high-penetrance PVs." (PMID 40805171, 2025). "BARD1, RAD51C and RAD51D explain 0.31% of the breast cancer polygenic variance." (PMID 36162851, 2022). "At least eight genes were found to be significantly associated with breast cancer risk: BRCA1 (MIM#113705), BRCA2 (MIM#600185), ATM (MIM#607585), BARD1 (MIM #601593), CHEK2 (MIM#604373), PALB2 (MIM#610355), RAD51C (MIM#602774), and RAD51D (MIM#602954)." (PMID 36139699, 2022). "Notably, a recently published study of the Breast Cancer Association Consortium (BCAC) with more than 60,000 female BC patients and more than 53,000 controls has demonstrated that protein truncation RAD51D variants are associated with a moderately increased BC risk." (PMID 36292468, 2022). "Other genes with moderate, low, or uncertain penetrance that have been implicated in breast cancer, RECQL, RAD51B, ERCC3, MRE11A, RAD51D, BARD1, and NBN, had a yield of 0.3% (n = 7), 0.3% (n = 7), 0.3% (n = 6), 0.3% (n = 6), 0.2% (n = 4), 0.2% (n = 4), and 0.1% (n = 3), respectively." (PMID 35971132, 2022). "Other epidemiological studies have reported associations between RAD51D germline variants and breast cancer risk regardless of the subtype of breast cancer." (PMID 34838098, 2021). "Similarly to other genes such as BARD1, RAD51D, BRIP1, and RAD51C, FANCM is emerging as a breast cancer predisposing factor conferring a greater risk specifically for these breast cancer subtypes." (PMID 31991861, 2020). "Studies on TN breast cancer patients showed associations of breast cancer with mutations in moderate penetrance breast cancer susceptibility genes FALB2, BARD1, BRIP1, RAD51C, and RAD51D." (PMID 30249004, 2018). "RAD51D showed significant methylation difference among the four breast cancer subtypes." (PMID 28424414, 2017).
breast cancer (continued). "In further analysis of the individual 29 genes methylation in subtypes using the Kruskal–Wallis Rank Sum test, only RAD51D gene showed significant methylation difference (P = 0.026) among the four subtypes in breast cancer with the lowest methylation level in basal-like tumor." (PMID 28424414, 2017). "Recently, another member of the RAD51 family of paralogs, RAD51D, was found to be mutated in women affected by familial ovarian cancer, with or without breast cancer." (PMID 22415235, 2012). "By means of this approach, we successfully mapped SREs in the breast cancer (BC) susceptibility genes BRCA2 (MIM#600185), including exon 17 with a GC-5′ss, CHEK2 (MIM#604373), and RAD51D (MIM#602954)." (PMID 39518003, 2024). "Nor was it large enough to address the variant detection rates for the ovarian susceptibility genes RAD51C and RAD51D that have previously been excluded as breast cancer susceptibility genes, but which were more recently confirmed as breast cancer genes just reaching two-fold relative risk." (PMID 34439310, 2021). "PRMT5 expression was moderately to strongly correlated (Pearson score ≥ 0.4) with established DDR genes such as BRCA1, BRCA2, RAD51, RAD51D, RAD51AP1, FANCA, and FANCI across 125 ovarian and breast cancer cell lines." (PMID 37861290, 2023). "However, several of our premenopausal breast cancer patients carried germline variants of unknown/uncertain significance (VUSs) in eight different breast cancer susceptibility genes, namely BRCA1, BRCA2, CHEK2, RAD51C, RAD51D, ATM, BRIP1, and PMS2." (PMID 36011273, 2022). "Breast cancer (BC) risk is significantly associated with pathogenic variants in at least eight susceptibility genes: BRCA1 (MIM#113705), BRCA2 (MIM#600185), PALB2 (MIM#610355), ATM (MIM#607585), CHEK2 (MIM# 604373), BARD1 (MIM#601593), RAD51C (MIM#602774), and RAD51D (MIM#602954)." (PMID 41230741, 2026). "No PGVs were seen in the breast cancer susceptibility genes RAD51C, RAD51D, or BARD1, all of which are known to be associated with triple-negative breast cancer, although not all patients had multigene panel tests including these genes." (PMID 39964682, 2025). "HRD extends beyond BRCA1/BRCA2 mutations to include non-BRCA genes (RAD51C/RAD51D, BRIP1, BARD1, ATM, PALB2), broadening actionable targets across ovarian and breast cancer subtypes, including HER2-positive (30–40%) and luminal subtypes (15–25%)." (PMID 40864792, 2025). "Using the breast cancer study as an example, it was found that the known eight famous genes—BRCA1, BRCA2, PALB2, BARD1, RAD51C, RAD51D, and ATM—in breast cancer research and practice actually lead to very low accuracy in predicting breast cancer status at the stage of diagnosis." (PMID 36298522, 2022). "In this study, we did not detect the RAD51C, RAD51D, FANCM, or PALB2 mutations among male breast cancer patients." (PMID 28874143, 2017). "Given the relatively low frequency of RAD51C, RAD51D, FANCM, and PALB2 mutations among unselected female breast cancer patients, the absence of the studied mutations in the MBC series was not unexpected." (PMID 28874143, 2017).
breast cancer (continued). "However, two of the human alternative transcripts of RAD51D have been identified in tumor derived cells, including an EST from a mammary tumor (DN997215) that corresponds to the RAD51DΔ3 isoform." (PMID 19327148, 2009). "However, no consensus was reached for recontact regarding breast cancer risk management in intermediate penetrance CSGs (ATM, CHEK2, RAD51C, RAD51D or BARD1)." (PMID 41159931, 2025). "The coding region of the RAD51D gene was analysed in 175 BRCA1/2-negative families with family histories of both ovarian and breast cancer ascertained from two Canadian and two Belgian institutions." (PMID 22415235, 2012). "Whether in HR+ or HR− subtype, HER2-positive breast cancer was characterized by gains in 17q12 (ERBB2, CDK12, HNF1B, RAD51D), and almost no gains of 17q12 were present in the other subtypes." (PMID 37264417, 2023).
Lynch syndrome (17 papers, 2017 to 2025). An autosomal dominant hereditary neoplastic syndrome characterized by the development of colorectal carcinoma and a high risk of developing endometrial carcinoma, gastric carcinoma, ovarian carcinoma, renal pelvis carcinoma, and small intestinal carcinoma. "Overall, 14.6% had mutations in BRCA1 or BRCA2, 3.3% had mutations in other BRCA–Fanconi anemia genes (BRIP1, PALB2, RAD51C, RAD51D, BARD1), and 0.4% had mutations in mismatch repair genes linked to Lynch syndrome." (PMID 32679669, 2020). "The most significant risk factor for OC development are germline pathogenic/likely pathogenic variants (GPVs) in OC predisposition genes (including BRCA1, BRCA2, BRIP1, RAD51C, RAD51D, Lynch syndrome genes, or BRIP1), which contribute to the development of over 20% of all OC cases." (PMID 38069345, 2023). "Of these, five mutations (9.26%, 5/54) were in homologous recombination repair (HRR) pathway genes, including PALB2 (1.85%, 1/54), BLM (1.85%, 1/54), NBN (1.85%, 1/54), RAD51C (1.85%, 1/54), and RAD51D (1.85%, 1/54), and one mutation was in MSH3 (1.85%, 1/54) related to Lynch syndrome." (PMID 33194720, 2020). "In addition to RAD51C, RAD51D and BRIP1 genes, it would be appropriate for an OC panel to also include PALB2 and Lynch Syndrome genes going forward." (PMID 34503154, 2021).
prostate carcinoma (16 papers, 2019 to 2025). A carcinoma that arises from epithelial cells of the prostate gland. "BRCA2 variants were the most prevalent at 5.3%, and variants in ATM, CHEK2, PALB2, BRCA1, and RAD51D were also more common among men with lethal prostate cancer." (PMID 36446039, 2022). "Of all RAD51 paralogs, the germline RAD51C and RAD51D variants can be found in both pancreatic cancer and prostate cancer, at a rate lower than 0.5%." (PMID 35563100, 2022). "The BRIP1 p.Arg798Ter and RAD51D p.Lys91Ilefs mutations were also shown to be a moderate-risk allele for prostate cancer and BC, respectively." (PMID 32359370, 2020). "In fact, germline RAD51D variants and susceptibility to prostate cancer has also been described." (PMID 32756499, 2020). "This clinical trial will include advanced/relapsed ovarian, breast, pancreatic, and prostate cancer patients who can be treated with PARPis and HER2-negative breast cancer patients with BRCA1/2, PALB2, RAD51C, and RAD51D mutations." (PMID 40521389, 2025). "Prostate cancer patients who have mutations in the DNA repair pathway (such as BRCA1, BRCA2, ATM, RAD51D and PALB2) have been shown to be significantly more likely to have advanced disease than patients without these mutations." (PMID 31915536, 2019). "Only in prostate cancer, however, RAD51D is altered in up to 4% of somatic samples." (PMID 35563100, 2022). "Moreover, there is good evidence from prostate cancer that the PARPi olaparib is effective in tumours with alterations in RAD51C, RAD51D, CHEK2, PALB2, RAD54L, and BARD1." (PMID 34680387, 2021). "Germline or somatic mutations in DNA damage repair (DDR) genes, such as BRCA2, CHEK2, ATM, RAD51D, BRCA1, and PALB2, have been described in around 20–25% of advanced prostate cancer patients, which involved in aggressive disease and poor outcomes in these patients." (PMID 33413230, 2021). "In several tumor types, particularly breast, ovarian, pancreatic, and prostate cancers, a strong correlation was observed between increased gLOH and biallelic alterations in other HR genes beyond BRCA1 and BRCA2, including BARD1, PALB2, FANCC, RAD51C, and RAD51D." (PMID 37761329, 2023).
Fanconi anemia (15 papers, 2015 to 2024). Fanconi anemia (FA) is a hereditary DNA repair disorder characterized by progressive pancytopenia with bone marrow failure, variable congenital malformations and predisposition to develop hematological or solid tumors. "HRD is an emerging biomarker defined by the mutations of BRCA1/2 genes, along with other Fanconi anemia pathway genes (RAD51D, NBN, and ATM)." (PMID 35983074, 2022). "Most detected variants affected the Fanconi anemia/DNA repair pathway (34%, ATM, FANCA, FANCI, MLH1, MSH6, POLE, RAD51C, RAD51D) followed by mutations altering the SWI/SNF (SWItch/sucrose non-fermentable) complex (22%, ARID1A and SMARCA4)." (PMID 34200508, 2021). "Deficiency in several of the classical human RAD51 paralogs [RAD51B, RAD51C, RAD51D, XRCC2 and XRCC3] is associated with cancer predisposition and Fanconi anemia." (PMID 31584931, 2019). "These genes include the Fanconi anemia pathway genes: FANCA, PALB2, BRIP1, RAD51C and XRCC2 and non-Fanconi anemia genes: ATM, CHEK2, NBN, RAD50, RAD51B, and RAD51D." (PMID 28202063, 2017).
triple-negative breast carcinoma (11 papers, 2015 to 2025). An invasive breast carcinoma which is negative for expression of estrogen receptor (ER), progesterone receptor (PR), and human epidermal growth factor receptor 2 (HER2). "We report a young female with a triple-negative breast cancer stage cT4bN3M0 and a hereditary pathogenic mutation in RAD51D." (PMID 36185283, 2022). "Pathogenic germline mutations in BRCA1, BRCA2, PALB2, RAD51C, and RAD51D, all of which are involved in the HR pathway, are known to confer high or moderate penetrance susceptibility to ovarian and/or triple-negative breast cancer." (PMID 34635660, 2021). "Pathogenic germline mutations in the RAD51 paralog genes RAD51C and RAD51D, are known to confer susceptibility to ovarian and triple-negative breast cancer." (PMID 34635660, 2021). "There is also some previous evidence that variants in RAD51D may predispose specifically to triple negative breast cancer." (PMID 34439310, 2021). "Out of the genes that have a role in the BRCA1/2 HR pathway, NCCN Guidelines (version 2.2021) indicate that the risk of triple negative breast cancer is potentially increased in patients with P/LP variants in BRIP1, RAD51C and RAD51D." (PMID 35710434, 2022). "Similarly, the high FNR and UR by ultrasound in RAD51D mutation carriers might result from their BRCA1-like phenotypes, i.e. higher proportion of triple-negative breast cancer (5/8) and higher Ki67 proliferation fractions (6/8 higher than 30%) in this study." (PMID 34336698, 2021). "Five other members belonging to the family of homologous recombination repair genes were upregulated by PAC in triple-negative breast-cancer cells (RAD54L, XRCC3, RAD51D, FEN1, and TOP3A) but only RAD54L is common in both types of cell lines (MCF-7 and MDA-MB-231)." (PMID 37298600, 2023).
breast ovarian cancer (8 papers, 2015 to 2025). "First, a RAD51D deletion that most likely is a germline (Class 4) variant, since it has been observed repeatedly (>5×) in oncogenetic screening of breast ovarian cancer families." (PMID 34680387, 2021). "On the other hand, there are no reports of an association between RAD51D and lymphomas; however, it is a well-established susceptibility gene in Breast-Ovarian Cancer, Familial 4 and Hereditary Breast Ovarian Cancer Syndrome." (PMID 32211398, 2020).
pancreatic cancer (7 papers, 2020 to 2025). "MGPTs generally cover at least 10 common HR-related genes such as ATM, BARD1, BRCA1, BRCA2, BRIP1, CHEK2, NBS1 (NBN), PALB2, RAD51C, and RAD51D, all of whose germline alterations are associated with BRCAness phenotypes for predisposition to breast, ovarian, prostate, or pancreatic cancer." (PMID 35008774, 2021). "Pancreatic cancer showed an exceptionally high biallelic loss in HRR genes, with BRCA1, CDK12, FANCC, PPP2R2 A, RAD51 C, RAD51D, RAD52, WRN, and XRCC3 all presenting 100% biallelic loss." (PMID 40420266, 2025). "Except for MSH3, the rest of the germline mutant genes in non-BRCA carriers with TNBC were involved in the HRR pathway, including BLM, PALB2, NBN, RAD51C, and RAD51D, with the mutation rate of 9.26% (5/54), which increased the risk of other cancers, such as PLAB2 for pancreatic cancer." (PMID 33194720, 2020).
serous ovarian cancer (6 papers, 2013 to 2025). "RAD51D mutations have been implicated in the transformation of normal fallopian tube epithelial (FTE) cells into high-grade serous ovarian cancer (HGSOC), one of the most prevalent and aggressive gynecologic malignancies." (PMID 38255960, 2024). "For example, susceptibility to high-grade serous ovarian cancer (HGSOC) is driven by mutations in genes that are involved in DNA double strand break repair (BRCA1, BRCA2, BRIP1, RAD51D and RAD51C), and as a consequence these tumors are highly genomically unstable." (PMID 28881617, 2017). "There are currently seven serous ovarian cancer patient samples listed with HELQ homozygous deletion, which is more than found for the RAD51 paralogs, except RAD51D." (PMID 24005565, 2013).
hereditary ovarian cancer (5 papers, 2012 to 2022). "The second gene featuring pathogenic variants in our sample, RAD51D (paralog of RAD51), has recently been identified as a moderately penetrant gene in hereditary ovarian cancer." (PMID 28591191, 2017).
serous adenocarcinoma (5 papers, 2012 to 2025). An adenocarcinoma that is characterized by the presence of papillary patterns and cellular budding. "It has been reported that ~18% of OC, particularly high-grade serous adenocarcinoma, is caused by germline genetic variants such as BRCA1/2, BRCA1-interacting protein C-terminal helicase 1 (BRIP1), and RAD51 paralog D (RAD51D)." (PMID 34064977, 2021). "All RAD51D carriers had high-grade serous carcinoma, compared to 51.5% in the NCR." (PMID 40428378, 2025). "Exome capture and DNA sequencing of 316 high-grade serous adenocarcinomas, however, did not identify any mutations in RAD51D, although 20% of tumours carried a germline or somatic mutation in BRCA1 or BRCA2." (PMID 22415235, 2012).